CAPN2 (calpain 2)
Description:
Calcium-regulated non-lysosomal thiol-protease which catalyzes limited proteolysis of substrates involved in cytoskeletal remodeling and signal transduction. Proteolytically cleaves MYOC at 'Arg-226'. Proteolytically cleaves CPEB3 following neuronal stimulation which abolishes CPEB3 translational repressor activity, leading to translation of CPEB3 target mRNAs (By similarity).
Synonyms: CANPL2; mCANP; CANPml; CANP2
Tractability: Small molecule: a high-quality ligand is known; it has a binding pocket of medium quality; it belongs to a druggable protein family. Antibody: its Gene Ontology location is reachable by antibodies, with high confidence; UniProt places it where antibodies can reach, with medium confidence. PROTAC: ubiquitination databases record sites on it; its protein half-life has been measured; a small molecule that binds it is known.
Target class: Protease; Enzyme; Cysteine protease C2 family; Cysteine protease CA clan; Cysteine protease
Gene: Protein-coding gene on chromosome 1 (223,701,593 to 223,776,018, forward strand). Ensembl gene ENSG00000162909.
Subcellular location: Cytoplasm; Cell membrane
Subcellular location (Human Protein Atlas): Connecting piece; Cytosol; Mid piece; Principal piece
Pathways (Reactome):
Cellular responses to stimuli: High laminar flow shear stress activates signaling by PIEZO1 and PECAM1:CDH5:KDR in endothelial cells; Turbulent (oscillatory, disturbed) flow shear stress activates signaling by PIEZO1 and integrins in endothelial cells
Disease: Deregulated CDK5 triggers multiple neurodegenerative pathways in Alzheimer's disease models
Extracellular matrix organization: Degradation of the extracellular matrix
Gene Ontology:
Molecular function: calcium-dependent cysteine-type endopeptidase activity; calcium-dependent cysteine-type endopeptidase inhibitor activity; protein binding; cysteine-type peptidase activity; cytoskeletal protein binding; calcium ion binding; enzyme binding; peptidase activity; protein-containing complex binding
Biological process: negative regulation of focal adhesion assembly; protein catabolic process; cellular response to amino acid stimulus; proteolysis; regulation of cytoskeleton organization; vascular endothelial cell response to laminar fluid shear stress; vascular endothelial cell response to oscillatory fluid shear stress; behavioral response to pain; cellular response to interferon-beta; cellular response to lipopolysaccharide; female pregnancy; positive regulation of cardiac muscle cell apoptotic process; positive regulation of myoblast fusion; positive regulation of phosphatidylcholine biosynthetic process; protein autoprocessing; protein catabolic process at postsynapse; regulation of interleukin-6 production; response to hydrogen peroxide; response to hypoxia; response to mechanical stimulus; synaptic vesicle endocytosis
Cellular component: calpain complex; cytosol; endoplasmic reticulum; extracellular exosome; focal adhesion; Golgi apparatus; membrane raft; perinuclear endoplasmic reticulum; plasma membrane; pseudopodium; cortical actin cytoskeleton; cytoplasm; dendrite; chromatin; external side of plasma membrane; lysosome; neuronal cell body; nucleus; postsynapse; presynapse
Genetic constraint (gnomAD): Loss-of-function variants: 60 observed, 72.53 expected, observed/expected ratio (o/e) 0.83, 90% interval 0.67 to 1.03. The upper end of that interval is the gene's LOEUF score, 1.03, which puts it in group 4 of 6, group 1 being the genes least tolerant of losing a copy. Missense variants: 656 observed, 745.36 expected, observed/expected ratio (o/e) 0.88, 90% interval 0.82 to 0.94. Synonymous variants: 286 observed, 298.86 expected, observed/expected ratio (o/e) 0.96, 90% interval 0.87 to 1.05.
Homologues: Orthologues: macaque CAPN2 (99% identical), chimpanzee CAPN2 (99% identical), mouse Capn2 (94% identical), dog CAPN2 (94% identical), rat Capn2 (94% identical), rabbit CAPN2 (93% identical), pig CAPN2 (93% identical), guinea pig CAPN2 (90% identical), tropical clawed frog capn2 (73% identical), zebrafish capn2l (69% identical), Caenorhabditis elegans clp-1 (35% identical), Caenorhabditis elegans clp-7 (33% identical), and 6 more. Paralogues in human: CAPN1 (63% identical), CAPN8 (61% identical), CAPN11 (53% identical), CAPN3 (50% identical), CAPN9 (49% identical), CAPN12 (43% identical), CAPN14 (36% identical), CAPN5 (31% identical), CAPN13 (30% identical), CAPN6 (27% identical), CAPN10 (25% identical), CAPN7 (23% identical), and 8 more.
Diseases named in the same sentence as CAPN2 in open-access papers:
CAPN2 is named in the same sentence as 106 diseases in open-access papers, as found by Europe PMC text mining. Sharing a sentence is not in itself a finding about the gene and the disease. The quoted sentences say what the papers report.
breast carcinoma (21 papers, 2014 to 2025). "Unlike in basal‐like breast cancer, CAPN2 expression showed minimal impact on the risk of other subtypes of breast cancer, highlighting the potential significance of calpain 2 as a critical target only in TNBC." (PMID 40151834, 2025). "Among basal‐like breast cancer patients with high gene expression of CAPN2 (encoding calpain 2), there was a tendency toward lower OS, distant metastasis‐free survival (DMFS), and relapse‐free survival (RFS)." (PMID 40151834, 2025). "An interesting observation of this study is that low calpain-9 expression is associated with disease-specific survival, whereas high expression of calpain-1 and calpain-2 are associated with poor breast cancer prognosis in other studies." (PMID 25539577, 2014). "In breast cancer high calpain-1 and calpain-2 expression has been associated with adverse clinical outcome." (PMID 25539577, 2014). "High calpain-2 expression in breast cancer is associated with poor survival in patients with triple negative or basal-like phenotype tumours; and high expression of calpain-1 can predict response following adjuvant trastuzumab therapy." (PMID 25539577, 2014). "These persistent molecular differences suggest spontaneous weaning as the optimal model for healthy mammary gland regression, whereas forced weaning sustains alterations in calpain-2 and regulatory miRs that may increase post-partum breast cancer risk." (PMID 41226539, 2025). "In the short lactation model by forced weaning, persistent effects on regulatory nodes such as calpain-2, miR-10b and miR-143/145 may contribute to increased risk of postpartum breast cancer (PPBC)." (PMID 41226539, 2025). "Furthermore, accumulation of nuclear calpain-2 has been associated to breast cancer cell proliferation." (PMID 37795261, 2023). "During lactation CAPN2 is associated with E-Cadherin on epithelial junctions, putatively clearing cell-cell connections to enable cell shedding into the lumen, however it becomes nuclear localized in breast cancer cells." (PMID 36242657, 2022). "High caspase-3/high calpain-1, high caspase-3/high calpain-2 and high caspase-3/low calpastatin expression significantly associated with adverse breast cancer-specific survival in the total patient cohort; and combinational caspase-3/calpain-1 has important prognostic value in basal-like patients." (PMID 27798717, 2017). "The aim of this study was to investigate the expression of calpain-1, calpain-2 and calpastatin in diagnostic, core biopsy specimens from women with large but operable primary breast cancer who were subsequently treated with neoadjuvant chemotherapy prior to surgical excision of residual tumour." (PMID 27323818, 2016). "The expression of calpain-1, calpain-2 and calpastatin was determined in diagnostic core biopsy samples taken from patients with large but operable breast cancer or locally advanced breast cancer who subsequently received neoadjuvant chemotherapy prior to surgical resection." (PMID 27323818, 2016). "Expression of the calcium-activated protease isoforms calpain-1 and calpain-2 has been correlated with cell migration and invasion in vitro, metastatic potential in preclinical mouse models of cancer, and breast cancer prognosis in patients." (PMID 40940726, 2025). "Studies indicated that LIPH had a higher expressed level in breast tumor tissue, and it affected the distant metastasis of breast cancer by regulating CAPN2 and paxillin." (PMID 37745080, 2023). "Depletion of CAPN2 or CAPNS1 by knockdown experiments in breast carcinoma cell lines reduced tumor growth in mouse orthotopic xenografts." (PMID 37795261, 2023). "Through the modulation of PP2A/Akt/FoxO3a pathway, CAPN2 silencing induces the expression of cyclin-dependent p27Kip1 kinase inhibitor and reduces breast carcinoma cell proliferation." (PMID 37795261, 2023). "Knockdown of CAPN2 mRNA expression reduced breast cancer cell invasion by regulating invadopodia dynamics, that is associated with metastasis." (PMID 35625741, 2022).
breast carcinoma (continued). "Taken together, this data suggests a breast cancer-specific subcellular distribution and role of CAPN2." (PMID 36242657, 2022). "Our experiments indicate that differential CAPN2 expression according to the breast cancer subtype is an important determinant for its nucleolar localization in tumor cells." (PMID 34381117, 2021). "The expression of calpain-2 was significantly upregulated when TM induced ERS in human breast cancer cells." (PMID 34604209, 2021). "Calpain-2 expression increased gradually with breast cancer progression in MMTV-PyMT mice, in accordance with expression changes in FN and EMT markers." (PMID 31000696, 2019). "In highly metastatic breast cancer cells, it was found that calpain-2 plays an important role in the cleavage of talin and focal adhesion turnover, which affects the migration of breast cancer cells in stiff tumor environments." (PMID 30427911, 2018). "The same pattern of calpain-2 distribution was also observed in a human breast cancer cell line suggesting that the nucleolar calpain-2 localization was not cancer-type specific." (PMID 29507677, 2018). "Aberrant expression of calpain family members has been implicated in tumour progression in a number of cancers and expression of calpain-1 and calpain-2 in breast cancer has been shown to be important in patient prognosis." (PMID 25539577, 2014). "The calpain system in general has been implicated in tumour progression, including altering cellular migration, survival and apoptosis; and expression of calpain-1, calpain-2 and calpastatin have been shown to be important in breast cancer." (PMID 25539577, 2014). "Notably, the correlation between CAPN2 and mesenchymal genes in basal‐like breast cancer was more pronounced than in other subtypes of breast cancer." (PMID 40151834, 2025). "In addition, the forest plot of CAPN2 univariate Cox analysis by molecular subtype demonstrates that CAPN2 expression increases the hazard ratio (HR) in basal‐like breast cancer." (PMID 40151834, 2025). "In contrast, calpain-2 played an important role in the nucleocytoplasmic trafficking of forkhead box protein P1 (FOXP1) via the PI3K-AKT pathway in breast cancer patients; cytoplasmic relocalization of FOXP1 correlated with reduced overall survival in breast invasive ductal carcinoma patients." (PMID 37795261, 2023). "The pro-tumoral environment might trigger the molecular switch from the physiological calpain-2/E-cadherin to the metastatic calpain-1/E-cadherin-cleavage observed in breast cancer cell lines." (PMID 37795261, 2023). "Hence, targeting calpain-1 and calpain-2 was proposed as a novel therapeutic strategy for mammary tumors." (PMID 37795261, 2023). "CAPN2 might be an important target with therapeutic potential for the design of inhibitors of the LIMK1/CFL1 signaling pathway in breast cancer." (PMID 34381117, 2021). "It has been reported that calpain-2 (CAPN2) regulates invadopodia and breast cancer invasion, promotes tumor growth and the proliferation of cancer cells in the mammary carcinoma through PI3K-Akt-FoxO-p27(Kip1) signaling, and is required for glioblastoma cell invasion." (PMID 31884422, 2019). "Patients with high caspase-3/high calpain-1 expression, high caspase-3/high calpain-2 expression, high caspase-3/low calpastatin expression, or high caspase-8/low calpain-1 expression had significantly worse breast cancer-specific survival (P = 0.005, 0.049, 0.02, and 0.02 respectively)." (PMID 27798717, 2017). "We have previously shown that high calpain-2 expression is associated with worse prognosis in patients with basal-like or triple-negative diseases and that calpain-1 expression is associated with trastuzumab response in HER2+ breast cancer patients." (PMID 27798717, 2017). "In conclusion, high calpain-2 and low calpastatin expression is associated with improved breast cancer-specific survival in non-inflammatory large but operable primary breast cancer treated with neoadjuvant chemotherapy." (PMID 27323818, 2016).
breast carcinoma (continued). "In addition to breast cancer, calpain-1 and calpain-2 expression has been shown to be altered in a number of other tumour types such as ovarian, pancreatic and gastric." (PMID 25539577, 2014). "Accumulating evidence has indicated that CAPN2, a calcium-activated protease, could participate in tumor progression and carcinogenesis in multiple cancer types including prostate cancer, ovarian cancer, breast cancer and hepatocellular carcinoma." (PMID 29228653, 2017). "Calpain 2 (CAPN2) and protein disulfide-isomerase A3 (PDIA3) have been identified in exosomes derived from breast cancer cells." (PMID 36076942, 2022). "This study has demonstrated that low expression of calpain-2 and high expression of calpastatin determined in diagnostic core biopsy samples is significantly associated with adverse breast cancer-specific survival in non-inflammatory large but operable primary breast cancer." (PMID 27323818, 2016). "Deletion of CAPN2 in breast cancer cells leads to lack of cofilin phosphorylation, mitotic defects, and multinucleated cells." (PMID 36242657, 2022). "Finally, high expression of CAPN2 and aberrant activation of the LIMK1/CFL1 axis found in breast cancer have been positively correlated with cancer development and metastasis." (PMID 34381117, 2021). "Translational studies have revealed that high calpain-2 expression correlates with adverse outcomes in basal-like or triple-negative breast cancer, while high calpain-1 expression correlated with poor relapse-free survival in HER2+ breast cancer." (PMID 30279968, 2018). "While high calpain-2 and low CAST expression was associated with improved survival in patients with non-inflammatory breast cancer treated with neoadjuvant chemotherapy, high calpain-1 and high CAST expression in the inflammatory group was associated with improved breast cancer survival." (PMID 37795261, 2023). "The expression of calpain-1, calpain-2 and calpastatin was determined using immunohistochemistry on core biopsy samples, in a cohort of large but operable inflammatory and non-inflammatory primary breast cancer patients treated with neoadjuvant chemotherapy." (PMID 27323818, 2016). "Furthermore, there have been no reports on the activity of CLIP4, CAPN2, CRLF1, CYBRD1, PHF10, and TRHDE in breast cancer or chemoresistance, thus making them new candidates for understanding breast cancer, the EMT, and chemoresistance." (PMID 27094684, 2016).
prostate carcinoma (12 papers, 2011 to 2025). A carcinoma that arises from epithelial cells of the prostate gland. "Calpain 2 has been linked to the AKT signaling pathway in conditions such as castration‐resistant prostate cancer, renal cell carcinoma, and non‐small cell lung cancer." (PMID 40151834, 2025). "In a prostate cancer study, abnormal CAPN2 expression was associated with cell metastasis and proliferation by activating AKT/mTOR signaling." (PMID 29228653, 2017). "Elevated calpain 1 levels are found in schwannomas, meningiomas, and renal carcinoma, while dysregulated calpain 2 is noted in colorectal adenocarcinomas, glioblastoma, prostate cancer, and renal cell carcinoma." (PMID 40151834, 2025). "One recent study shows that prolonged androgen deprivation leads to overexpression of calpain 2 in prostate cancer progression." (PMID 27206800, 2017). "Accumulated evidences have indicated that CAPN2 play a crucial role in the progression and prognosis of various cancers, including prostate cancers." (PMID 28280729, 2017). "In contrast, an another researcher found that CAPN2 mRNA was significantly upregulated in prostate carcinomas compared with the normal control prostate tissues." (PMID 28280729, 2017). "In fact, inhibition or downregulation of calpain 2 clearly decreased migration and invasion of DU-145 prostate cancer cells in vitro and in vivo." (PMID 24297527, 2014). "Endogenous target silencing was further evaluated with antibody based detection of calpain 2 (CAPN2) silencing on VCaP prostate cancer cells transfected for 72 h on a CSMA with 96 technical replicates of four different CAPN2 and control siRNAs." (PMID 21443765, 2011). "Therefore, our study firstly showed the relationship between CAPN2 expression and MMPs in prostate cancer cells." (PMID 28280729, 2017). "Furthermore, abnormal CAPN2 level was also detected in metastatic prostate cancer compared with normal tissues, and promoted prostate cells invasive and proliferative capabilities." (PMID 29228653, 2017). "Overexpression and enhanced activity of calpain-2 also induces an increase in the fragmental cleavage of AR and FlnA, which may contribute to the development of an aggressive phenotype of prostate cancer." (PMID 27689993, 2016). "Considering the multiple cellular functions of calpain 2, its abnormal high expression and enhanced activity may play important roles in prostate cancer progression including migration, invasion and metastasis during androgen deprivation therapy." (PMID 24297527, 2014). "The overexpression of calpain 2 and increased expression of FlnA may contribute to the development of an aggressive phenotype of prostate cancer." (PMID 24297527, 2014). "Hence, DMDP-1 & -2 induce CI-PCD in prostate cancer cell lines through calpain-2 and cathepsin B." (PMID 31969640, 2020). "It indicated that CAPN2 might act as oncogenic biomarkers and promote prostate cancer progression." (PMID 28280729, 2017). "We believe that CAPN2 may provide a new therapeutic strategy for treating prostate cancer patients." (PMID 28280729, 2017). "Our present data strongly support the concept that long-term androgen deprivation may push androgen-sensitive prostate cancer cells evolve into AR-negative, more aggressive, androgen-independent disease state, with overexpression of calpain 2 enhancing its activity." (PMID 24297527, 2014). "Therefore, the combination of calpain 2 inhibitor and androgen deprivation may provide new therapeutic strategy for patients to prevent or postpone prostate cancer progression." (PMID 24297527, 2014). "Meanwhile, calpain-2 was proven to contribute to the methylation of CRMP4′s promoter, repressing its transcription, thereby promoting the metastasis of prostate cancer by enhancing expression of vascular endothelial growth factor C." (PMID 35625600, 2022).